CD4 (CD4 molecule)
Diseases named in the same sentence as CD4 in open-access papers (continued):
Sharing a sentence is not in itself a finding about the gene and the disease.
ovarian carcinoma (262 papers, 2005 to 2026). A malignant neoplasm originating from the surface ovarian epithelium. "Owing to this, it was suggested that the CD8+/CD4+ (Treg) ratio is associated with a favorable prognosis in epithelial ovarian cancer." (PMID 36674491, 2023). "Intra-islet CD4+ TILs of omental metastases were the main risk factors associated with poorer survival in advanced epithelial ovarian cancer, and the highest infiltration was found in the stroma of the omental tissue." (PMID 37761986, 2023). "Our results demonstrated that the downregulation of SPTBN2 in ovarian cancer cases would reduce the risk of death when they were enriched in CD4+ T cells (p < 0.05) or dendritic cells (p = 0.067)." (PMID 34179092, 2021). "Their presence has been found to be associated with a good prognosis in ovarian cancer through the priming of CD4+ and CD8+ T cells and the production of tumor-specific IgGs." (PMID 34149794, 2021). "A higher ratio of CD8+ lymphocytes to Tregs (CD4+ CD25+ FOXP3+) in the TILs of epithelial ovarian cancer tissues is associated with a more favourable prognosis." (PMID 32937961, 2020). "Xiang and collaborators demonstrated that IL-17 in ovarian cancer is produced by CD4+ T cells and CD68+ macrophages, tumor-associated macrophages (TAM) in the ovarian CSC niche, and the IL-17 receptor is expressed in a population of CD133+ CSCs." (PMID 28819364, 2017). "In ovarian cancer, Curiel and colleagues initially showed a strong association of CD4+CD25+ T cells with poor survival." (PMID 24244610, 2013). "In the presence of IL-2, human ovarian cancer-associated CD4+ regulatory T cells have also been shown to convert into proinflammatory IL17-producing helper T cells in vitro." (PMID 23272176, 2012). "In this work, we investigate this hypothesis by examining the frequency of exhausted and senescent CD4+ T cells in peripheral blood, with the aim of determining whether these dysfunctional immune cell states are associated with ovarian malignant tumors." (PMID 40870871, 2025). "However, the CD4+T cell enriched/ CSGALNACT2high group was associated with a better prognosis of ovarian cancer patients, but the CD4+T cell decreased / CSGALNACT2high group predicted poor survival of ovarian cancer patients." (PMID 38082211, 2024). "However, the CD4+T cell enriched/ CSGALNACT2high group was associated with a better prognosis of ovarian cancer patients." (PMID 38082211, 2024). "Our work demonstrates the central role of HLA-DR-restricted peptide presentation of the tumor antigen Mesothelin and of CD4+ T-cell responses for tumor immune surveillance, and underlines Mesothelin as a prime target antigen for novel immunotherapeutic approaches for ovarian carcinoma patients." (PMID 35565389, 2022). "Because humoral response to NY-ESO-1 is tightly associated with specific CD8+ and CD4+ T-cell responses against the antigen and is a frequently observed antigen in ovarian cancers, we evaluated NY-ESO-1 serology as a surrogate for the presence of T cell responses." (PMID 32676168, 2020). "In contrast, presentation of HLA class II-restricted peptides and, thus, CD4+ T cell-mediated immunosurveillance, which we recently found to associate with improved outcome in ovarian cancer, appears to play a subsidiary role, as an indolent disease course could not be confirmed by prolonged PFS." (PMID 36230581, 2022). "Moreover, the number of CD4+Foxp3+ Tregs was higher in our B7-H4-positive specimens than that in our B7-H4-negative ones, which reflects a previously reported positive association between Tregs and B7-H4 in ovarian cancers." (PMID 34651047, 2021). "Regulatory T (Treg) cells, a subset of CD4+ T lymphocytes, are mediators of immunosuppression in cancer, and, thus, variants in genes encoding Treg cell immune molecules could be associated with ovarian cancer." (PMID 27533245, 2016).
ovarian carcinoma (continued). "Because of the importance of CD4+ Tregs and a role for inherited factors in outcome, we assessed whether common inherited variation related to CD4+ Treg-related genes was associated with ovarian cancer outcome following standard of care therapy." (PMID 23382860, 2013). "Tumor-associated lymphocytes (TALs) from ovarian cancer patients confirmed that both CD8+ and CD4+ T cells exhibited elevated levels of LAG-3 and PD-1." (PMID 40649775, 2025). "A study showed that Tregs are more sensitive to GX-15 than CD4-Teff in peripheral blood monocytes from ovarian cancer patients, so GX-15 significantly inhibits Treg function with little or no impact on Teff function." (PMID 40216744, 2025). "CD4+ T cells influence ovarian cancer progression, particularly through the Th2 subpopulation, which secretes IL-4 and correlates with poor prognosis." (PMID 40136652, 2025). "Nevertheless, the role of CD4+ T cells in the ovarian cancer (OC) tumor microenvironment remains significantly understudied." (PMID 41008548, 2025). "In an article investigating the phenotype of tumor-infiltrating lymphocytes (TILs) in ovarian cancer, researchers showed that CD4+ TILs in high-grade serous ovarian cancer (HGSOC) consists mostly of Tregs." (PMID 40216744, 2025). "In summary, this study delineated the terminal differentiation trajectories of tumor-infiltrating CD4+ T cells within the ovarian cancer microenvironment, identifying CD4+ regulatory T cells (Tregs) as the predominant subtype." (PMID 41008548, 2025). "In this study, we leveraged scRNA-seq to dissect the cellular diversity of gene expression in tumor-infiltrating CD4+ T cells, aiming to inform precision medicine approaches for ovarian cancer treatment." (PMID 41008548, 2025). "CD4+CD25+Foxp3+ Tregs are induced by COX-2/PGE-2 secretion from ovarian cancer cells, promoting tumor growth." (PMID 40136652, 2025). "Clinical studies have also confirmed that CD4 + CD25 + Tregs are recruited to tumor sites by recombinant human C-C motif chemokine 22 protein (CCL22) secreted by ovarian cancer cells, resulting in the accumulation of CD4 + CD25 + Tregs in cancer tissues." (PMID 40587482, 2025). "In ovarian cancer, CD4/6 inhibition by abemaciclib improves anti-PD-1 response via driving CD8+ cytotoxic T cell and B cell recruitment to the tumor microenvironment." (PMID 40175357, 2025). "In BRCA1-mutated ovarian cancers, the main functions identified were related to the immune system, such as MHC assembly, CD4 and CD25 regulation, and regulation of the interferon gamma pathway, among others." (PMID 40647506, 2025). "TIGIT, an inhibitory checkpoint molecule, is upregulated on CD4+ Tregs in murine ovarian cancer models." (PMID 40703514, 2025). "In line with previous reports indicating that ovarian cancer TILs predominantly exhibit an effector memory phenotype, our data showed that the majority of CD4+ and CD8+ T cells in the expanded TIL products were effector memory cells." (PMID 41280919, 2025). "In this research, scRNA-seq was employed to delineate the subtypes and differentiation trajectories of tumor-infiltrating CD4+ T cells in ovarian cancer." (PMID 41008548, 2025). "In our study, we show an increased frequency, particularly of CD4+ T cells with an exhausted phenotype, in malignant ovarian tumors compared to benign tumors, and in addition, with healthy volunteers." (PMID 40870871, 2025). "The combination of the ROMA score with the expression of PD-1+ and Tim-3+ in CD4+ T cells creates a simple yet highly effective model to differentiate between benign and malignant ovarian tumors." (PMID 40870871, 2025). "In an immunological investigation of patients with ovarian cancer, the presence of NY‐ESO‐1 autoantibodies was associated with increased tumor‐infiltrating CD8+, CD4+, and FoxP3+ cells." (PMID 38896069, 2024).
ovarian carcinoma (continued). "Our findings suggest a correlation between AP3S1 and CD4 + T cells in ovarian cancer, which provides new avenues for further investigating the role of AP3S1 in tumor immunity." (PMID 38609993, 2024). "It was demonstrated in the murine ovarian cancer model that artesunate promoted miRNA-142 expression in peripheral CD4+ T cells and Th1 differentiation from CD4+ T cells." (PMID 39195233, 2024). "As a “cold” type cancer, ovarian cancer, especially platinum-resistant subtype, shows low infiltration of cytotoxic immune cells, such as CD4 + T cell and CD8 + T cell." (PMID 38308314, 2024). "An NY‐ESO‐1 peptide ESO157–170 can be recognized by HLA‐DP4‐restricted CD4 T cells and HLA‐A2‐ and A24‐restricted CD8 T cells to stimulate Th1 and Th2 CD4+ T cell responses in patients with epithelial ovarian cancer." (PMID 38896069, 2024). "We also applied SPOT to an ovarian cancer dataset, which corroborated the prognostic importance of CD4 T cell and macrophage colocalization, as well as macrophage and B cell colocalization." (PMID 38950184, 2024). "Chemotactic assays in vitro suggested that high level of CCL1 and CCL18 in the TME of ovarian cancer contributed to the increased infiltration of CD4+CCR8+ Tregs into tumor tissues." (PMID 37950246, 2023). "In the TME of ovarian cancer, CCR8 was the dominant chemokine receptor expressed on CD4+ TILs which was closely related to the pathological process of ovarian cancer." (PMID 37950246, 2023). "Previous studies found m7GRGs expression in ovarian cancer (OC) is significantly correlated with immune cells (involving CD4+ memory resting T cells, plasma cells, and Macrophages M1)." (PMID 36816047, 2023). "In the current RROS, we confirmed that most of the included ovarian cancer patients (94.7%) had IHC positivity for CD4+, CD8+, and/or CD45+ immune cells." (PMID 37761986, 2023). "CD4+ and CD8+ tumor-infiltrating lymphocytes (TILs) have been associated with improved OS and progression-free survival (PFS) in all epithelial ovarian cancers, including the high-grade serous, mucinous, clear cell, and endometrioid types." (PMID 37761986, 2023). "Studies have shown that CDK4/6 inhibition combined with PD-1 blockade treatment has higher CXCL10 and CXCL13 levels and CD8 + and CD4 + T cell activity than monotherapy-treated ovarian cancer." (PMID 37005667, 2023). "Ovarian cancer cells, CD4+ and CD8+ memory T cells, and M0 macrophages overexpress the arginine CAT1 transporter." (PMID 37274280, 2023). "To demonstrate the tumor microenvironment, we found that the positive expressions of PD-L1 on ovarian cancer cells were significantly associated with high percentage of TILs that express CD8 and CD4." (PMID 36604635, 2023). "Olaparib maintenance treatment can significantly decrease the IL‐6 and TNF‐α level, and increase IFN‐γ level and the CD4+/CD8+ ratio in patients with recurrent ovarian cancer." (PMID 37904699, 2023). "In an ovarian cancer model, artesunate, a medication used to treat malaria, induced Th1 cell differentiation from CD4+ T cells and showed enhanced proapoptotic effects on ovarian cancer cells by upregulating miR-142 and suppressing SIRT1 levels." (PMID 38116009, 2023). "IL-6-dependent differentiation of CD4+ regulatory T cells has been stimulated by ovarian cancer ascites fluid in vitro." (PMID 36860657, 2023). "PD-L1 expressions are positively associated with better prognosis in ovarian cancer and tumor infiltrating lymphocytes presenting CD8 and CD4." (PMID 36604635, 2023). "The presence of CD4+ CXCL13+ T cells early in TLS formation in ovarian cancer also supports a role for these cells in co-ordinating adaptive immune responses and facilitating development of TLS to maximise their efficiency." (PMID 37520560, 2023). "RAD51AP1 was reported to be associated with immune infiltration of ovarian cancer, and upregulation of RAD51AP1 accompanied by accumulated Th2 cells, but decreased CD4 + T cells and CD8 + T cells." (PMID 36197550, 2022).
ovarian carcinoma (continued). "As a protein highly expressed in OC, we found that SLC7A1 was positively correlated with CD4+ resting memory cells, CD8+ effector memory cells, cancer-associated fibroblasts (CAFs), and M0 macrophages in ovarian cancer by immune evaluation (P < 0.05)." (PMID 36131790, 2022). "Among them, the expression of macrophages M0, macrophages M1, Tregs, and CD4+ T-cells were significantly upregulated in cancer, indicating that they are important factors involved in ovarian cancer immunity." (PMID 36172179, 2022). "Alternatively, we demonstrated that the injection of CXCL13 induced TLS formation accompanied by the inhibition of tumor growth in mouse models, and that CD4+ T cells were the major source of CXCL13 in human ovarian cancer TLS." (PMID 35552285, 2022). "Overall, our data demonstrate that systemic inhibition of SPHK1 reduced both S1P‐mediated signaling and ovarian cancer growth by activating both CD4 and CD8 positive T cells." (PMID 35289120, 2022). "who, in a murine model of ovarian cancer, showed that artesunate induced Th1 differentiation of CD4+ via miR-142-mediated downregulation of sirtuin 1, resulting in enhanced ovarian cancer apoptosis." (PMID 36700235, 2022). "During ovarian cancer progression, different types of T cells are recruited to the tumor lesion for tumor immune response, including CD4+ cells, CD8+ T cells." (PMID 36437919, 2022). "Previous studies have shown that tumor immune infiltration in ovarian cancer is cohort and subtype dependent, and activated CD4+T and CD8+T tumor infiltrating lymphocytes are associated with good OS of ovarian cancer." (PMID 36081665, 2022). "The results showed that activated mast cells, resting CD4 memory T cells, and neutrophils were significantly correlated with poor prognosis of ovarian cancer." (PMID 36081665, 2022). "This identified signature was significantly associated with overall survival, radiation therapy, age, clinical stage, cancer status, and immune cells (involving CD4+ memory resting T cells, plasma cells, and Macrophages M1) of ovarian cancer patients." (PMID 36545327, 2022). "For example, EVs from patients with ovarian cancer inhibit, in vitro, the activation of CD4+ and CD8+ T lymphocytes." (PMID 35741003, 2022). "Antitumor effects of combined anti-PD-1 mAb and anti-OX40 mAb in a murine ovarian cancer model increased the activity of effector CD4+ and CD8+ T cells and attenuated the action of immunosuppressive CD4+FoxP3+ regulatory T cells in tumor sites." (PMID 34768776, 2021). "Here, using phenotypic, transcriptomic, and functional approaches, we characterized CD4 T cell exhaustion in patients with head and neck, cervical, and ovarian cancer." (PMID 33332284, 2021). "CD4+ T-cells displayed further elevation of TIM-3 in ovarian cancer recurrence, suggesting TIM-3 as a biomarker for early detection as well as detection of recurrence." (PMID 34940257, 2021). "Increased CD4+ to CD8+ population shifts and decreased IL-17 from Th17 effector T cells within ovarian cancer ascites have been associated with compromised survival." (PMID 34503128, 2021). "In contrast, we noticed the positive associations of CXCR2 with the abundance of CD8+ naïve T cell, CD4+ central memory T cell, CD4+ Th2 T cell, CD4+ Th1 T cell, common lymphoid progenitor, and B cell plasma across ovarian cancer." (PMID 34840630, 2021). "Our findings collectively indicate that in germline BRCA ovarian cancer patients, PARPi treatments significantly elevate STAT3 activity in tumor cells and tumor-associated immune cells, including B cells, CD4+ and CD8+ T cells, and CAFs." (PMID 34956861, 2021). "An abundance of cytotoxic CD8+ T cells as well as CD4+ in ovarian cancer is a prognostic indicator of greater PFS and OS." (PMID 33923934, 2021).
ovarian carcinoma (continued). "CD4 T helper cells can inhibit the transformation of immunosuppressive regulatory T cells in ovarian cancer." (PMID 34109184, 2021). "CD4 T cells induce the host immune response through dendritic cells in patients with MHC class II-negative ovarian cancer." (PMID 34109184, 2021). "The microarray expression values of ovarian cancer were used to calculate the abundances of six immune infiltrates (B cells, CD4+ T cells, CD8+ T cells, Neutrophils, Macrophages, and Dendritic cells) via the TIMER algorithm." (PMID 34249076, 2021). "We further found that the expression of DOCK4 is correlated with the levels of CD4+ T cell infiltration, dendritic cell infiltration, and neutrophil infiltration in these ovarian cancer patients." (PMID 33613670, 2021). "Following this observation, we did a meta-analysis of mDCs and HLA-DR+CD4+ pDCs in PBMCs from prostate cancer (PC) and ovarian cancer (OvCa) patients and frequencies were compared to those identified in healthy donors (HD)." (PMID 33995353, 2021). "Further researchers confirmed this suggestion, showing an increased percentage of CD4+/IL-17+ lymphocytes among cells infiltrating ovarian cancer." (PMID 32148497, 2020). "Elucidating the regulatory mechanisms of energy metabolism and functionality in CD4+ T cells will provide insights for the development of novel immunotherapies for ovarian cancer (OC)." (PMID 33102225, 2020). "In both peripheral blood and peritoneal fluid, the percentage of CD4+ lymphocytes expressing IL-17 was significantly lower (p < 0.0001) in the ovarian cancer group than in the benign ovarian tumor group." (PMID 32148497, 2020). "Our analysis demonstrated a CD4+ T cell activation induced in ovarian cancer patients vaccinated with autologous DCs loaded with HOCl-treated autologous tumor lysates in a phase I clinical study." (PMID 32498431, 2020). "Subsets of Siglec-9+ expressing CD8+ and CD4+ TILs have also been found in patients with epithelial ovarian cancer." (PMID 32937961, 2020). "The hOX40 KI mouse model displayed an expression pattern of hOX40 largely reflecting that seen on healthy hPBMCs and samples from ovarian cancer patients with a hierarchy of expression of Treg>CD4+>CD8+." (PMID 33428585, 2020). "Studies of pancreatic cancer, oesophageal squamous cell carcinoma, and ovarian cancer showed that high CD4+T cell infiltration can improve prognosis." (PMID 32767974, 2020). "Prior studies have established the notion that CD4+ /CD8+ T-cells are capable of recognizing cancer antigens and positively associated with favorable RFS in ovarian cancer." (PMID 32723974, 2020). "The highest percentage of CD4+ lymphocytes expressing IL-17 was detected among CD4+ T cells infiltrating ovarian cancer and it was significantly higher (p=0.001) compared to PB." (PMID 32148497, 2020). "In conclusion, the findings of this study illustrated that artesunate promotes Th1 differentiation from CD4+ T cells by down-regulating Sirt1 through miR-142, thereby enhancing cell apoptosis in ovarian cancer." (PMID 31038546, 2019). "The percentages of apoptosis of Th1/CD4+ T cells and ovarian cancer cells were analyzed by flow cytometry." (PMID 31038546, 2019). "The differentiation-induced and artesunate-treated CD4+ T cells were then co-cultured with mouse ovarian cancer cell line ID8." (PMID 31038546, 2019). "Results from a previous report revealed that high CD4/Treg ratio correlated with longer survival in a group of patients with ovarian cancer, which is consistent with our findings." (PMID 30971280, 2019). "Artesunate promoted Th1 differentiation from CD4+ T cells by down-regulating Sirt1 through miR-142, thereby enhancing cell apoptosis in ovarian cancer." (PMID 31038546, 2019). "Towards this goal, blocking antibodies against CD39 or CD73 showed dampened adenosine production by ovarian cancer cell lines and restored cytotoxicity of NK cells and stimulated proliferation of CD4+ T cells in co-culture with ovarian cancer cells." (PMID 31652269, 2019).